ENSG00000288669 (novel protein, readthrough CD209 - CLEC4G)
Gene: Protein-coding gene on chromosome 19 (7,728,958 to 7,745,662, reverse strand). Ensembl gene ENSG00000288669.
Genetic constraint (gnomAD): Missense variants: 14 observed, 23.15 expected, observed/expected ratio (o/e) 0.6, 90% interval 0.4 to 0.94. Synonymous variants: 5 observed, 9.89 expected, observed/expected ratio (o/e) 0.51, 90% interval 0.26 to 1.06.